NAMPT (nicotinamide phosphoribosyltransferase)
Diseases named in the same sentence as NAMPT in open-access papers (continued):
Sharing a sentence is not in itself a finding about the gene and the disease.
pancreatic cancer (continued). "Moreover, Kaplan-Meier analysis conducted using the UCSC Xena browser indicated a correlation between high levels of NAMPT expression and poor overall survival in pancreatic cancer patients (p = 0.0454)." (PMID 38625917, 2024). "In light of the potential role of IDO1 as a driver of hostile TME in PDAC and NAD+ as a key coenzyme in anti-tumor immune response, this review urges focus on extensive research and initiation of clinical trials using IDO1 and NAMPT inhibitors in pancreatic cancer in the future." (PMID 37456260, 2023). "Notably, SIRTs are upregulated along with NAMPT in several solid cancers, including breast, prostate, gastric, colorectal, liver, and pancreatic cancers." (PMID 38116009, 2023). "Pancreatic ductal adenocarcinoma cells, leukemic cells, and pancreatic neuroendocrine tumor cells all displayed comparable effects, and in both subtypes of pancreatic cancer, concurrent treatment with mTOR inhibitors enhanced the antiproliferative effects of NAMPT inhibition." (PMID 36160449, 2022). "This work shows that combining metformin, a drug that inhibits complex I and reduces the NAD+/NADH ratio, with FK866, a drug that inhibits the NAD salvage enzyme NAMPT, triggers a better anticancer response than that obtained with either drug alone in several pancreatic cancer cell lines." (PMID 36428689, 2022). "However, neither SIRT1 nor PARP-1 (another NAD+ dependent enzyme) play a significant role on the effect of NAMPT inhibition on pancreatic cancer cells." (PMID 33042011, 2020). "In both pancreatic cancer subtypes, the antiproliferative effect of NAMPT inhibition could be potentiated with concurrent mTOR inhibitor treatment." (PMID 32010616, 2019). "Also, the results reinforce the key role of NAD metabolism and NAMPT as targets in pancreatic cancer." (PMID 29156703, 2017). "NAMPT overexpression has been recently found in colorectal, breast, prostatic, gastric, esophageal, pancreatic cancers, and specific NAMPT inhibitors might be adjuvant therapeutic modalities." (PMID 25946974, 2015). "Therefore, NAMPT inhibitors may be used as coadjuvants with gemcitabine, the current therapy administered to pancreatic cancer patients." (PMID 40805270, 2025). "Likewise, concurrent overexpression of CD38 and NAMPT inhibition had synergistic effect on growth suppression in pancreatic cancer, suggesting a critical dependence of cancers on NAD+ that may be explored therapeutically." (PMID 35677882, 2022). "In total, 39 genes were identified as mutually differentially expressed and concordant in expression with the NAMPT-silenced model (P < 0.05 after Benjamini-Hochberg adjustment) in at least three out of four cancer types: lung cancer, colon cancer, pancreatic cancer, and thyroid cancer." (PMID 25146220, 2014). "NAMPT and NAPRT levels are significantly increased in pancreatic cancer tumors, and its increased expression correlated with worse prognosis." (PMID 40805270, 2025). "Several enzymes in NAD metabolic pathway such as nicotinamide phosphoribosyl transferase (NAMPT), NAD + kinase, and the NAD-dependent sirtuin family have been reported to be altered in pancreatic cancer." (PMID 41391757, 2025). "Overall, taken together, these results indicate that MAP17 expression correlated with the increased expression of the two most important and limiting enzymes of NAD biosynthesis, NAMPT and NAPRT, which are also upregulated in pancreatic cancer." (PMID 40805270, 2025). "FK866 inhibits NAMPT, disrupting NAD+ production and impairing energy metabolism, leading to apoptosis in MiaPaCa-2 pancreatic cancer cells." (PMID 39337621, 2024). "For instance, we demonstrated that NAPRT-expressing ovarian and pancreatic cancers are resistant to NAMPT inhibition, but downregulation of NAPRT significantly depletes intracellular NAD stores and sensitizes these tumors to NAMPT inhibitors." (PMID 34068917, 2021).
pancreatic cancer (continued). "Pharmacologic and genetic targeting of NAMPT, the key enzyme in the NAD salvage synthesis pathway, inhibits cell growth and survival of pancreatic cancer cells." (PMID 33042011, 2020). "NAMPT is one of the two enzymes regulating the NAD+ salvage pathway, a vital pathway allowing pancreatic cancer cells to maintain their metabolism, notably in hypoxic conditions." (PMID 28927421, 2017). "Due to the central role of NAMPT in PDAC metabolism, the present work was aimed to obtain preclinical data for STF-118804 in pancreatic cancer models." (PMID 29156703, 2017). "Thus, targeting NAMPT may not only disturb the salvage pathway on which pancreatic tumor cells heavily rely, but may also “normalize” blood vessels in the tumor, a phenomenon that will improve the delivery and efficacy of anticancer treatments and relieve immunosuppression." (PMID 28927421, 2017). "In addition, we found that MAP17 expression positively correlated with NAMPT and NAPRT expressions in different pancreatic cancer databases." (PMID 40805270, 2025). "The NAMPT inhibitor, FK866, was evaluated in various nude mouse xenograft models (e.g., ovarian cancer, pancreatic cancer, and colon cancer), and showed strong efficacy in phase I and II clinical trials for advanced or metastatic solid tumors, refractory lymphoma, and advanced pancreatic cancer." (PMID 39337621, 2024). "Kaplan-Meier analysis showed that overall survival was significantly shorter in pancreatic cancer patients with high NAMPT expression levels, whereas overall survival was not affected by NMNAT2 expression." (PMID 38625917, 2024). "Indeed, it has been reported that inhibition of NAMPT decreases NAD levels and attenuates glycolysis in different cancer types, including pancreatic cancer cells." (PMID 36428689, 2022). "Abrogating the regeneration of NAD by inhibiting nicotinamide phosphoribosyltransferase disrupts aerobic glycolysis and leads to pancreatic cancer cell growth inhibition in vitro and in vivo, although no tumor regressions were seen in in vivo models." (PMID 31225458, 2018). "For example, FK866, a non-competitive highly specific inhibitor of NAMPT, shows potent anti-tumor activity both in vitro and in vivo on pancreatic cancer samples overexpressing NAMPT mRNA." (PMID 28927421, 2017). "Nicotinamide phosphoribosyltransferase (NAMPT) is the rate-limiting enzyme responsible for this conversion, and this enzyme has been shown to be overexpressed in many types of cancer, including lung, prostate, gastric, colorectal, and pancreatic cancer." (PMID 29156703, 2017). "Some NAMPT inhibitors, such as FK866, CHS828, GEN618, and OT-82, have been shown to significantly inhibit cell growth in both in vitro and in vivo models of various cancers, including pancreatic cancer, non-small cell lung cancer, lymphoma, prostate cancer, and breast cancer." (PMID 39337621, 2024). "However, NAMPT expression has not been well studied in human PDA with only one small study including 23 patient-derived pancreatic cancer cell lines." (PMID 30856230, 2019). "In pancreatic cancer cells, the salvage pathway appears to be the predominant NAD synthesis pathway (as opposed to the De Novo synthesis pathway), partly because the enzyme NAMPT is overexpressed in human pancreatic cancers compared to normal pancreatic tissue." (PMID 36428689, 2022).
leukemia (29 papers, 2013 to 2025). A malignant (clonal) hematologic disorder, involving hematopoietic stem cells and characterized by the presence of primitive or atypical myeloid or lymphoid cells in the bone marrow and the blood. "Combination of etoposide with FK866, an NAMPT-specific inhibitor, causes increased death of leukemia cell lines compared to etoposide alone." (PMID 37746249, 2023). "Previous studies also report that some AML leukemia cells show high NAMPT dependence, although mechanisms underlying death of those cells after NAD depletion by NAMPT inhibition likely differ from those seen in NECs5,6." (PMID 38092728, 2023). "A recent study showed that inhibition of HDAC8 or SIRT6 induces DNA repair deficiencies in homologous recombination and NHEJ pathways in leukaemia-initiating cells, and such DNA repair deficiencies are synergistic with nicotinamide phosphoribosyl transferase (NAMPT) targeting." (PMID 34395273, 2021). "In addition, an elevated QPRT expression in the GMX1778-resistant HT1080 fibrosarcoma cell line and in the FK866-resistant CCRF-CEM leukemia cell line was the underlying resistance mechanism to these NAMPT inhibitors (through the activation of de novo NAD+ biosynthesis)." (PMID 38396769, 2024). "Daporinad inhibits NAMPT, an enzyme whose suppression has been found effective in hindering leukemia progression in B-ALL cell lines like SUP-B15, aligning with our prediction." (PMID 38614131, 2024). "In agreement with our previous studies on APO866, a prototype NAMPT inhibitor, we found that the new NAMPT inhibitors are highly toxic towards leukemia (AML and ALL), lymphoma (Burkitt) and multiple myeloma (MM) cells." (PMID 36838885, 2023). "The results of the current investigation confirmed earlier studies in others types of tumors including pancreatic, gastric, and leukemia, showing that suppressing NAMPT activity lowers cell proliferation." (PMID 36899911, 2023). "We demonstrated that nicotinaldehyde can be used as a novel NAD precursor by leukemia cells to circumvent the NAD depletion typically induced by NAMPT inhibition blocking the NAD salvage pathway." (PMID 36765744, 2023). "Nicotinaldehyde supplementation replenishes the intracellular NAD level in leukemia cells treated with NAMPT inhibitor APO866 and prevents APO866-induced oxidative stress, mitochondrial dysfunction and ATP depletion." (PMID 36765744, 2023). "Here, we provide for the first time in vivo evidence that gut bacteria, despite being hosted at distant sites from a tumor, can protect leukemia/lymphoma cells from NAMPT inhibitor-induced death." (PMID 35396381, 2022). "Here we show that the amount of NAM or NA contained in food and of bacteria from the gut microbiota can severely modulate the anti-leukemia activity of a NAMPT inhibitor." (PMID 35396381, 2022). "PJ34 significantly decreases APO866-mediated cell death in dose-dependent manner, suggesting the implication of PARP1 activation in the anti-leukemia effects of the NAMPT inhibitor." (PMID 31803365, 2019). "We observed that NAMPT is expressed in all tumor types tested, although the leukemia cell lines (NB4, ML2 and HL-60) showed weaker expression." (PMID 26675378, 2016). "NAMPT is overexpressed in different types of cancer, including prostate, gastric, breast and ovarian cancer, gliomas, leukemia, lymphoma and myeloma." (PMID 26658104, 2016). "In line with these notions, several studies have highlighted a strong activity of NAMPT inhibitors in preclinical models of inflammatory and malignant disorders, including leukemia." (PMID 26542945, 2015).
leukemia (continued). "Nurse-like cells (NLC) represent a population of leukemia-associated macrophages expressing CD14, CD45, HLA-DR, CD33, and CD68, which are induced by CLL cells through nicotinamide phosphoribosyl transferase (NAMPT) and high-mobility group protein B1 (HMGB1) signaling." (PMID 37064123, 2023). "It has been reported that NAMPT inhibition sensitizes leukemia cells for other chemotherapies, and could be a novel strategy to enhance treatment index." (PMID 37746249, 2023). "As tumor cells always have very high intracellular NAD turnover, which is supportive for the increased metabolic demands in rapid proliferation by generating more ATP/energy, NAMPT overexpression is rather common in many types of tumor, including leukemia and solid tumor." (PMID 28097126, 2016). "Interestingly, results from a recent study in preclinical leukemia models revealed functional antagonism between NAMPT and PARP inhibitors, suggesting that cell type specific differences in how these pathways interact may be present." (PMID 32010616, 2019). "In leukemia cells, the phosphorylation of EIF2S1 also inhibits the activities of nicotinamide phosphoribosyltransferase (NAMPT), a factor known to regulate cancer cell metabolism." (PMID 28018022, 2016). "Finally, novel antibody–drug conjugates with NAMPT inhibitors as payloads have suppressed tumor growth in xenograft models of breast cancer (HER2-expressing MDA-MB-453 cells) and leukemia (B7H3-expressing THP-1 cells)." (PMID 38396769, 2024). "Here, we report a previously undescribed function of nicotinaldehyde in NAD metabolism and its negative impact on the therapeutic efficacy of NAMPT inhibitors in leukemia treatment." (PMID 36765744, 2023). "Of interest, we provide the first description of the potential negative impact of nicotinaldehyde on the anti-leukemia activities of NAMPT inhibitors." (PMID 36765744, 2023). "Here we show that the NAMPT inhibitor APO866 is a very potent inducer of different types of ROS/RNS, including cO2/mO2, H2O2, NO and hROS and that these strongly contribute to its anti-leukemia activity." (PMID 31803365, 2019). "NAMPT inhibition was also found to increase the efficacy of Tumor Necrosis Factor-Related Apoptosis Inducing Ligand (TRAIL), HDAC inhibitors, P-glycoprotein-1 (Pgp) inhibitors and of Rituximab, an anti-CD20 antibody, in leukemia cells." (PMID 26658104, 2016). "Whether and how the microbiota may alter the anti-lymphoma/leukemia properties of NAMPT inhibitors has not been addressed." (PMID 35396381, 2022). "Interestingly, NAMPT, the most upregulated of the metabolic proteins, replenishes NAD+ levels and is a cofactor required for glycolysis, oxidative phosphorylation, and fatty acid synthesis implicating a high energy demand signal from leukemia cells upon stroma contact." (PMID 38851813, 2024). "FK866, a non-competitive inhibitor of NAMPT, has been shown to reduce NAD+ levels and suppress glycolysis in human leukemia cells, reduce viability of both solid and hematologic cancers, and reduce leukemic disease burden in vivo." (PMID 40526635, 2025).
diabetes (28 papers, 2011 to 2025). "Considering that NAD is a major coenzyme in bioenergetic processes, NAMPT is biologically indispensable, and it has been implicated in a variety of inflammatory disorders, such as tumorigenesis, diabetes, rheumatoid arthritis and sepsis." (PMID 36792688, 2023). "However, NAMPT has different roles in various inflammatory-associated diseases related to infection, diabetes, and anti-microbial responses." (PMID 40722609, 2025). "Nicotinamide phosphoribosyltransferase (NAMPT) is associated with aging and diabetes." (PMID 36397950, 2022). "NAMPT also contributed to the regulation of insulin secretion in the pancreatic β-cells and diabetes mellitus." (PMID 34041361, 2021). "Visfatin, also known as extracellular pre–B-cell colony–enhancing factor (PBEF) and nicotinamide phosphoribosyltransferase (Nampt), is an adipocytokine whose circulating levels are enhanced in metabolic disorders, such as type 2 diabetes mellitus and obesity." (PMID 22073309, 2011). "NAMPT could therefore also represent a pathomechanistic link, how periodontitis affects systemic diseases, such as diabetes mellitus and cardiovascular diseases." (PMID 24058270, 2013). "Additionally, NAMPT levels were significantly downregulated in mice fed a high-fat diet, which may lead to functional changes in mitochondria, thereby aggravating diabetes." (PMID 39859466, 2025). "Finally, alteration of NAMPT/visfatin/PBEF levels has been observed in diabetes and obesity." (PMID 29546048, 2018). "Nicotinamide phosphoribosyltransferase (NAMPT) is a crucial rate-limiting enzyme in the NAD salvage pathway and is dysregulated in metabolic diseases, such as diabetes." (PMID 39859466, 2025). "After adjusting for age, BMI, and diabetes duration in the multivariable model, CD38, NAMPT, and SIRT1 remained strong independent predictors of albuminuria, confirming that their associations were not confounded by these clinical covariates." (PMID 41470091, 2025). "This study seeks to systematically examine blood concentrations and gene expression of CD38, NAMPT, and SIRT1 across several stages of albuminuria in individuals with type 2 diabetes mellitus." (PMID 41470091, 2025). "Additionally, the complications of diabetes resulting from poor vascular function—such as retinopathy, hypertension, and myocardial infarction—are due to low mobilization of endothelial progenitor cells caused by NAD+ deficiency in the nicotinamide phosphoribosyltransferase (NAMPT)-NAD+ pathway." (PMID 38399441, 2024). "In conclusion, our study suggests that glycemic fluctuation in diabetes causes more damage in peri-implantitis compared with uncontrolled hyperglycemia, through regulating TLR2/4-IRAK1-TRAF6 pathway but not NAMPT/SIRT1 signaling." (PMID 34401982, 2021).